TMEM200C (transmembrane protein 200C)
Synonyms: TTMA
Tractability: Antibody: UniProt predicts a signal peptide or a membrane-spanning region.
Gene: Protein-coding gene on chromosome 18 (5,882,072 to 5,896,084, reverse strand). Ensembl gene ENSG00000206432.
Subcellular location: Membrane
Subcellular location (Human Protein Atlas): Microtubules
Gene Ontology:
Cellular component: membrane
Genetic constraint (gnomAD): Loss-of-function variants: 0 observed, 0.78 expected, observed/expected ratio (o/e) 0, 90% interval 0 to 1.78. That is too few expected variants to judge how well the gene tolerates losing a copy. Missense variants: 608 observed, 503.78 expected, observed/expected ratio (o/e) 1.21, 90% interval 1.13 to 1.29. Synonymous variants: 296 observed, 222.29 expected, observed/expected ratio (o/e) 1.33, 90% interval 1.21 to 1.47.
Homologues: Orthologues: chimpanzee TMEM200C (98% identical), macaque TMEM200C (96% identical), pig TMEM200C (82% identical), rabbit TMEM200C (81% identical), rat Tmem200c (77% identical), mouse Tmem200c (77% identical), dog TMEM200C (77% identical), guinea pig TMEM200C (61% identical), tropical clawed frog tmem200c (47% identical), zebrafish TMEM200C (31% identical), Drosophila melanogaster CG12502 (16% identical), Caenorhabditis elegans R05D7.3 (11% identical). Paralogues in human: TMEM200A (22% identical), TMEM200B (12% identical).
Diseases named in the same sentence as TMEM200C in open-access papers:
TMEM200C is named in the same sentence as 4 diseases in open-access papers, as found by Europe PMC text mining. Sharing a sentence is not in itself a finding about the gene and the disease. The quoted sentences say what the papers report.
uveal melanoma (1 paper, 2021). A melanoma derived from melanocytes of the uveal tract. "TMEM200C is reported to be hypomethylated, and candidate oncogenes linked to early metastasis in uveal melanoma." (PMID 34956309, 2021).
TMEM200C also shares sentences with these, for which no sentence is quoted: Autoimmunity (1 paper); liver cancer (1); thyroid disease (1).